SIK3 (SIK family kinase 3)
Diseases named in the same sentence as SIK3 in open-access papers (continued):
Sharing a sentence is not in itself a finding about the gene and the disease.
osteoarthritis (4 papers, 2016 to 2023). A noninflammatory degenerative joint disease occurring chiefly in older persons, characterized by degeneration of the articular cartilage, hypertrophy of bone at the margins and changes in the synovial membrane. "Deletion of Sik3 in adult mice causes thickening of articular cartilage and resistance to surgically induced osteoarthritis, a phenotype associated with reduced expression of Col10 in the non-calcified zone of articular cartilage." (PMID 27009967, 2016). "Examining the effects of Sik3 deletion on age-associated osteoarthritis model in mice is for further study." (PMID 27009967, 2016). "The increase in chondrocyte number and cartilage growth associated with SIK3 KO/inhibition could be beneficial for the treatment of osteoarthritis, which is associated with reduced cartilage thickness." (PMID 36731029, 2023). "We show that either Sik3 deletion or intraarticular injection of mice with pterosin B inhibits chondrocyte hypertrophy and protects cartilage from osteoarthritis." (PMID 27009967, 2016). "Here we generate chondrocyte-specific salt-inducible kinase 3 (Sik3) conditional knockout mice that are resistant to osteoarthritis with thickened articular cartilage owing to a larger chondrocyte population." (PMID 27009967, 2016). "Collectively, our results suggest Sik3 regulates the homeostasis of articular cartilage and is a target for the treatment of osteoarthritis, with pterosin B as a candidate therapeutic." (PMID 27009967, 2016). "Recently, pterosin B was reported as a small molecule inhibitor of SIK3 with in vivo activity in a SIK3-dependent murine osteoarthritis model." (PMID 27759007, 2016). "On the basis of our results, we suggest that SIK3 regulates the homeostasis of articular cartilage and can be a target for the treatment of osteoarthritis, and that pterosin B can be the lead compound for relevant drugs." (PMID 27009967, 2016). "Here, the authors show that interfering with Sik3 signalling can increase the size of the chondrocyte population and reduce severity of a surgically induced mouse model of osteoarthritis." (PMID 27009967, 2016). "As SIK3 deficiency delayed chondrocyte hypertrophy it was suggested that the KO or inhibition of SIK3 may protect against osteoarthritis." (PMID 33861845, 2021). "It will clearly be of interest to investigate whether pan-SIK, or SIK3-specific inhibitors protect against osteoarthritis in mouse models of this disease." (PMID 33861845, 2021). "Indeed, there was thickening of the articular cartilage in adult SIK3 cKO mice due to increased chondrocyte proliferation and these mice were protected from developing osteoarthritis." (PMID 33861845, 2021). "Here we show that SIK3 is activated in human osteoarthritic cartilage, leading us to hypothesize that Sik3 is important for the development of osteoarthritis." (PMID 27009967, 2016). "An analysis of the effects of Sik3 deletion on aged mice with DMM surgery would further clarify whether Sik3 affects the development of osteoarthritis, since osteoarthritis is more common in the elderly." (PMID 27009967, 2016). "Because our Sik3Δ/Δ mice data suggested that Sik3 could be a target for treatment of osteoarthritis, we searched for compounds that inhibit Sik3 activity." (PMID 27009967, 2016). "We next examined whether Sik3 deletion affected the development of osteoarthritis in adult mice." (PMID 27009967, 2016). "Whether hedgehog signalling mediates effects of Sik3 on osteoarthritis is unexplored." (PMID 27009967, 2016). "It has been reported that the intra-articular injection of mice with Pterosin B protected against osteoarthritis and based on experiments in primary chondrocytes the mechanism was suggested to involve the PKA-dependent inhibition of SIK3 followed by its proteasomal degradation." (PMID 33861845, 2021). "Fourth and finally, other effects of pterosin B besides Sik3 inhibition cannot be ruled out as providing protection from osteoarthritis." (PMID 27009967, 2016).
acute myeloid leukemia (3 papers, 2019 to 2024). Acute myeloid leukemia (AML) is a group of neoplasms arising from precursor cells committed to the myeloid cell-line differentiation. "SIK2 has a role in tumorigenesis in prostate and ovarian cancers, and SIK2 and SIK3 promote the growth of acute myeloid leukemia (AML) by inhibiting HDAC4 function." (PMID 39139449, 2024). "Notably, the SIK inhibitor YKL-05-099 attenuated disease progression in two acute myeloid leukaemia (AML) mouse models, which was attributed to on-target inhibition of SIK3 based on overexpression of the SIK3 gatekeeper mutant in AML cells." (PMID 33861845, 2021). "Using kinase domain-focused CRISPR techniques, researchers screened all dependent kinase in acute myeloid leukemia (AML), focusing subsequent experiments on SIK3, which scored strongly in MOLM-13 and MV4-11 AML cells and in a more intermediate fashion in other AML cell lines." (PMID 30723708, 2019).
colitis (3 papers, 2023 to 2026). Inflammation of the colon. "Preclinical studies in mouse models of colitis, psoriasis, and arthritis demonstrated that SIK2/SIK3 inhibition reduced inflammatory activity and promoted immunoregulatory and tolerogenic-associated pathways." (PMID 41657312, 2026).
hypersomnia (3 papers, 2022 to 2025). A sleep disorder characterized by excessive sleepiness. "Accordingly, ABC-KO of exon 13 of Sik3 induced marked hypersomnia, 200-300 min increase in daily NREMS time accompanied by constitutively elevated NREMS δ power, similar to that of Sleepy mice carrying the germline Slp mutation." (PMID 35667851, 2022). "For example, ABC-KO of exon 13 of Sik3 induced hypersomnia in Sik3-E13flox/flox mice, whereas ABC-CRISPR of Slp/Sik3 largely reversed hypersomnia in Sleepy (Sik3Slp/+) mice." (PMID 35667851, 2022). "Whereas ABC-KO of exon 13 of Sik3 by AAV-Cre injection in Sik3-E13flox/flox adult mice phenocopies Sleepy (Sik3Slp/+) mice, ABC-CRISPR of Slp/Sik3 reverses hypersomnia of Sleepy mice, indicating a direct role of SLP/SIK3 kinase in sleep regulation." (PMID 35667851, 2022). "Because ABC-KO of exon 13 of Sik3 could induce hypersomnia in adult mice, we hypothesized that ABC-KO of Slp/Sik3 by triple-target CRISPR should rescue hypersomnia of Sik3Slp/+ mice." (PMID 35667851, 2022). "Sik3-deficiency in neurons decreases nonrapid eye movement (NREM) sleep time and electroencephalogram (EEG) delta power during NREM sleep, while Sik3Slp mice lacking a protein kinase A (PKA)-phosphorylation site, S551, show hypersomnia phenotype." (PMID 39656684, 2025).
psoriasis (3 papers, 2016 to 2026). An autoimmune condition characterized by red, well-delineated plaques with silvery scales that are usually on the extensor surfaces and scalp. "We found that CpG sites of C1orf106, DMBX1, and SIK3 mediate the genetic risk of psoriasis." (PMID 27980695, 2016). "Our data showed that SIK1 was upregulated in IMQ-induced psoriasis, but SIK2 and SIK3 showed similar expression compared with control mice." (PMID 39959414, 2025).
triple-negative breast carcinoma (3 papers, 2017 to 2023). An invasive breast carcinoma which is negative for expression of estrogen receptor (ER), progesterone receptor (PR), and human epidermal growth factor receptor 2 (HER2). "Double knockouts of SIK1 and SIK3 increase triple-negative breast cancer invasion, which agrees with the finding that SIK1 and SIK3 are involved in LKB1-mediated tumor suppression pathways." (PMID 36731029, 2023). "A previous study reported that curcumin exhibits antitumor activity in triple-negative breast cancer patient-derived xenograft tumor mice by inhibiting the expression of salt-inducible kinase 3 (SIK3)." (PMID 37124223, 2023). "Indeed, in triple-negative breast cancer tissues, SIK3 is highly expressed while SIK1 and SIK2 are reduced." (PMID 36731029, 2023). "Interestingly, we have shown higher expression of SIK3 in triple negative breast cancer cell lines (MDA-MB-231 and BT-20) which are known to exert treatment resistance." (PMID 28658303, 2017). "Identification of SIK3 could possibly offer novel therapeutic targets to treat triple negative breast cancers." (PMID 28658303, 2017). "It is of interest to note that triple negative breast cancer cell lines (MDA-MB-231 and BT-20) known for their high treatment resistance have shown statistically significant (p<0.05) higher expression of SIK3 compared to receptor positive cell lines (MCF-7 and AU565)." (PMID 28658303, 2017).
acute kidney injury (2 papers, 2017 to 2022). Sudden and sustained deterioration of the kidney function characterized by decreased glomerular filtration rate, increased serum creatinine or oliguria. "SERPINA4 and SERPINA5, but not BCL2 and SIK3 are associated with acute kidney injury in critically ill patients with septic shock." (PMID 35874763, 2022).
cholestasis (2 papers, 2012 to 2020). Impairment of the bile flow caused by obstruction within the liver, or outside the liver in the bile duct system. "We would again emphasize that the high-fat diet ameliorated cholestasis in Sik3−/− mice, indicating the importance of the process for nutrients rather than developmental defects in BA transportation." (PMID 22662228, 2012). "Sik3−/− mice present with a malnourished phenotype due to their reduced adaptation to excess nutrition, especially to cholesterol and CA, which eventually leads to severe cholestasis." (PMID 22662228, 2012). "However, we have to mention that the wild-type mice that were fed with a vitamin A-deficient diet for 6 months from weaning did not develop cholestasis (unpublished observation), indicating that the levels of vitamin A and its metabolites may be insufficient to explain all of the Sik3−/− phenotypes." (PMID 22662228, 2012). "Meanwhile, the high-fat diet ameliorated cholestasis in Sik3−/− mice without FA storage (in the liver and adipose tissues) or restoring the mRNA levels of genes involved in FA synthesis, such as Fasn." (PMID 22662228, 2012). "Hepatocytes in Sik3−/− embryos (E18.5) were not normal; notably, the hepatocytes were of a variable size, and a significant number of multinucleated hepatocytes were observed, suggesting liver damages due to embryonic cholestasis." (PMID 22662228, 2012).
fatty liver (2 papers, 2012 to 2025). "After 4 months, the wild-type mice developed fatty liver, while the livers of Sik3−/− mice had surface asperity and turned yellow." (PMID 22662228, 2012). "The low levels of liver TG in Sik3−/− mice might have prevented the development of fatty liver, while total cholesterol levels were low in the serum of Sik3−/− mice." (PMID 22662228, 2012).
leukemia (2 papers, 2016 to 2022). A malignant (clonal) hematologic disorder, involving hematopoietic stem cells and characterized by the presence of primitive or atypical myeloid or lymphoid cells in the bone marrow and the blood. "We identified 147 CRGs from 153 leukemia samples with only five observed in more than one sample (CEP164, DSCAML1, FXYD2, SIK3, and GRIA4)." (PMID 35945623, 2022).
Lipid metabolism disorders (2 papers, 2012 to 2014). "Lipid metabolism disorders in (Sik3−/−) mice were partially restored after 9-cis-retionic acid supplementation." (PMID 25060954, 2014). "Lipid metabolism disorders in Sik3−/− mice are ameliorated by the treatment with 9-cis-retinoic acid." (PMID 22662228, 2012).
lung cancer (2 papers, 2022 to 2025). A malignant neoplasm involving the lung. "Our data collectively indicated that WNK3 and SIK3 were positive PD-L1 regulators in lung cancer cells." (PMID 36357569, 2022).
pancreatic cancer (2 papers, 2022 to 2025). "Different from breast and pancreatic cancers, SIK3 serves as a tumor suppressor in ovarian and lung cancers." (PMID 39895792, 2025). "Moreover, SIK3 ​can protect pancreatic cancer cells from cytotoxic T-cell attack by triggering TNF-induced NF-κB translocation." (PMID 39895792, 2025).
Stroke (2 papers, 2022 to 2024). Sudden impairment of blood flow to a part of the brain due to occlusion or rupture of an artery to the brain. "Therefore, inhibition of SIK3 in Mi/MΦ may be a potential therapeutic target in stroke and other CNS diseases with accompanying white matter destruction." (PMID 35864266, 2022).
amyotrophic lateral sclerosis (1 paper, 2024). Amyotrophic lateral sclerosis (ALS) is a neurodegenerative disease characterized by progressive muscular paralysis reflecting degeneration of motor neurons in the primary motor cortex, corticospinal tracts, brainstem and spinal cord. "For instance, FN1 and SIK3 are associated with spondyloepiphyseal dysplasia, PADI2 is related to sclerosis, ERBB4 is connected to amyotrophic lateral sclerosis (ALS), and B3GNT2 and BACE1 are associated with muscular dystrophy and muscular inflammation, respectively." (PMID 38788487, 2024).
atherosclerosis (1 paper, 2020). A disease characterized by the build-up of fatty material and calcium deposition in the arterial wall resulting in partial or complete occlusion of the arterial lumen. "Since the SNPs at 11q23.3 region harbouring apolipoprotein coding genes namely APOA1, APOC3, APOA4, APOA5 and regulatory genes BUD13, ZPR1, SIK3 were found to be associated with defective lipid metabolism, this region was thought to play an important role in atherosclerosis and CAD risk." (PMID 33298998, 2020).
cardiac hypertrophy (1 paper, 2024). "Cardiac hypertrophy of the spontaneous hypertensive rats is associated with decreased cardiac expression of SIK1 and SIK3." (PMID 39081779, 2024). "Unlike the pro-hypertrophic role of SIK1, SIK3 functions as a suppressor of cardiac hypertrophy." (PMID 39081779, 2024).
epilepsy (1 paper, 2021). A brain disorder characterized by episodes of abnormally increased neuronal discharge resulting in transient episodes of sensory or motor neurological dysfunction, or psychic dysfunction. "Glial-specific inhibition of HDAC4, a central repressor of SIK3 signaling, results in a constitutively active glial buffering program that dramatically suppresses seizure and extends life span in a classic epilepsy model." (PMID 33646119, 2021).
gallstones (1 paper, 2014). Solid crystalline precipitates in the biliary tract, usually formed in the gallbladder, resulting in the condition of cholelithiasis. "In addition, recent studies showed that leptin and some metabolic kinase signalings, such as LKB1-AMPK and -SIK3 could regulate bile acid metabolism and might affect gallstone formation." (PMID 24598574, 2014).
Hypercalcemia (1 paper, 2023). An abnormally increased calcium concentration in the blood. "Ubiquitous/inducible SIK1/SIK2/SIK3 deletion caused modest increases in trabecular bone mass, with dramatic 1,25-vitamin D–mediated hypercalcemia." (PMID 36862513, 2023). "Humans with homozygous loss-of-function SIK3 mutations show mild PTH-independent hypercalcemia, and common SIK3 variants are associated with blood calcium levels, findings that confirm the relevance of our findings in human mineral metabolism." (PMID 36862513, 2023). "Global- and kidney-specific Sik2/Sik3 mutant mice showed Cyp27b1 upregulation, elevated serum 1,25-vitamin D, and PTH-independent hypercalcemia." (PMID 36862513, 2023).
lung fibrosis (1 paper, 2022). "Both SIK3 knockout and SIK3 kinase inactive knockin mice exhibit increased postnatal mortality and growth retardation, making them poorly suited for the analysis of SIK3 in lung fibrosis." (PMID 36309093, 2022). "Total SIK3 knockout mice have a developmental phenotype making them unsuitable for analysis in this model; however, we determined that conditional knockout of SIK3 in the immune system did not affect bleomycin-induced lung fibrosis." (PMID 36309093, 2022). "In contrast to this, SIK2 appears to be the predominant isoform regulating lung fibrosis, although a contribution from SIK3 cannot be ruled out." (PMID 36309093, 2022).
melanoma (1 paper, 2019). A malignant, usually aggressive tumor composed of atypical, neoplastic melanocytes. "Additionally, we noted a significant association of hypermethylation of cg09923443 (SIK3) and adverse histologic parameters in primary melanomas including ulceration and increased mitotic rate." (PMID 31888295, 2019).
non-small cell lung carcinoma (1 paper, 2025). A group of at least three distinct histological types of lung cancer, including non-small cell squamous cell carcinoma, adenocarcinoma, and large cell carcinoma. "While the loss of SIK3 facilitates tumor progression in non-small cell lung cancer 17, few studies have addressed the regulatory role of SIK3 in CRC." (PMID 39895792, 2025).
osteoporosis (1 paper, 2026). A condition of reduced bone mass, with decreased cortical thickness and a decrease in the number and size of the trabeculae of cancellous bone (but normal chemical composition), resulting in increased fracture incidence. "Therefore, direct small molecule SIK2/SIK3 inhibitors may represent a strategy to mimic PTH actions to treat different forms of osteoporosis." (PMID 41908158, 2026).
preeclampsia (1 paper, 2023). Preeclampsia is a hypertensive disorder of pregnancy that is characterized by new-onset hypertension with proteinuria presenting after 20 weeks of gestation, and depending on mild or severe forms may initially present with severe headache, visual disturbances, and hyperreflexia. "Therefore, circulating SIK3 detection might act as a preeclampsia prediction marker." (PMID 38203391, 2023).
respiratory failure (1 paper, 2012). The significant impairment of gas exchange within the lungs resulting in hypoxia, hypercarbia, or both, to the extent that organ tissue perfusion is severely compromised. "Because Sik3−/− mice had skeletal abnormalities, their early death was probably due to respiratory failure caused by thoracic dystrophy." (PMID 22662228, 2012).
sarcoma (1 paper, 2022). A usually aggressive malignant neoplasm of the soft tissue or bone. "Expression of SIK1 was the highest in DSRCT compared to other sarcomas, while expression levels of SIK2, SIK3 and LKB1 in DSRCT were similar to other sarcomas." (PMID 35443736, 2022).
serous ovarian cancer (1 paper, 2019). "In addition, in serous ovarian cancer, SIK3 expression is inversely correlated to ABCG2 expression, and patients with low SIK3 and high ABCG2 expression have worse prognosis than patients with high SIK3 and low ABCG2 expression." (PMID 31762812, 2019). "To confirm the clinical observation of chemosensitivity related to SIK3 expression, we selected SKOV3 and OVCAR4 cells from six serous ovarian cancer cell lines for further SIK3 knockdown experiments." (PMID 31762812, 2019).